TCF7 (transcription factor 7)
Diseases named in the same sentence as TCF7 in open-access papers (continued):
Sharing a sentence is not in itself a finding about the gene and the disease.
cancer (continued). "TCF7 is predicted to sponge miRNA (in cancer cells) to promote cancer invasion." (PMID 37190145, 2023). "Additionally, CD8+ TCF7+ T cells define stem-like T cells in cancer patients, have enhanced self-renewal, multipotency, and give rise to more terminally differentiated effector CD8+ T cells, further supporting our continuum model." (PMID 34663807, 2021). "Indeed, acute viral models have shown that loss of Ezh2 results in increased expression of memory-associated transcripts such as Tcf7, which is associated with stem-like CD8+ T cells in cancer." (PMID 33117406, 2020). "In addition, previous studies showed that miR-192 was involved in progression of human cancers through regulating expressions of target genes, such as Egr1 and TCF7." (PMID 32013999, 2020). "MIR159 was capable of inhibiting cancer proliferation by targeting TCF7." (PMID 31689969, 2019). "Tcf7 gene encodes the transcription factor TCF1 whose expression alone or in combination with the surrogate cell membrane molecule Ly108 permits a clear distinction of the three typical stages of the T cell differentiation linear model found in chronic infections and cancer." (PMID 37033927, 2023). "Subsequently, the Wnt signaling of cancer cells could be activated by TCF7." (PMID 29299179, 2017). "We found that the significantly activated regulons were involved in T cell biology (RORC, TCF7, NFATC1, and LEF1) or disease pathogenesis (IKZF2 for CD30+ TMF and BATF3 for cALCL) or reported cancer biology (POUZAF1 and TSHZ2)." (PMID 37790936, 2023). "A pan-cancer view revealed that LEF1, TCF3,TCF4, and TCF7 have aberrant expression andare potentially involvement in the tumorigenesis of various cancer types." (PMID 38100720, 2023). "This study aimed to establish a novel four‐gene signature (CD8A, CD8B, TCF7, and LEF1) to provide a prognostic immunotherapy biomarker for different cancers." (PMID 35588138, 2022). "To detect the logarithm fold change (logFC) in the expression of the four genes TCF7, LEF1, CD8A, and CD8B in different cancers, we investigated the transcriptomic profiles retrieved from the TCGA database." (PMID 35588138, 2022). "The prevalence of TCF7 methylation and CDK2NA methylation (except for CDK2NA in KIRP) were enriched in the later-onset cases across multiple cancer types." (PMID 34788626, 2021). "The gene BMX nonreceptor tyrosine kinase regulates differentiation and tumorigenicity of several types of cancer cells, and another gene (MLLT11, transcription factor 7 cofactor) was expressed in several leukemic cell lines." (PMID 30793795, 2019). "Moreover, in chronic infections and cancer, the TCF-1 (TCF-7) in supporting the stemness and self-renewal of T cells is of utmost importance." (PMID 40483533, 2025). "Furthermore, four gene signatures of TEX phenotype, terminal, GZMK+, OXPHOS- and TCF7+ TEX subtypes, were identified from pan-cancer single-cell sequencing data." (PMID 37113755, 2023). "Interestingly, CD8A, CD8B, TCF7, and LEF1 cannot serve as therapeutic targets for these cancers because of their different expression profiles." (PMID 35588138, 2022). "Additionally, TCF7+ (TCF1+) T cells (hereafter referred to as TCF7+ T cells) amplify immune responses and improve the response to immunotherapy in cancer." (PMID 35345446, 2022). "CFP1 upregulated expression of β-catenin, LEF1, TCF1/TCF7, c-MYC, TGFBR3, and TGFB1, and the cancer-promoting effects of CFP1 were not completely repressed by pathway inhibitors." (PMID 37735441, 2023).
infection (19 papers, 2014 to 2026). The state of being infected such as from the introduction of a foreign agent such as serum, vaccine, antigenic substance or organism. "To eliminate the influence of abnormal CD4 T cell responses attributed to Tcf7 deficiency on CD8 T cell function during infection, we depleted CD4 T cells via injecting mice with the depleting antibody GK1.5 before LCMV infection." (PMID 30814995, 2019). "This TCF7‐associated trait significantly reduces the emergence of the pathogenic triad, thereby mitigating age‐associated immunopathology manifested as increased infection risk and severity, comorbidities such as cardiovascular disease, and mortality." (PMID 40264357, 2025). "A parallel human infection challenge model with Salmonella typhi revealed that maintained SAS‐1high‐MAS‐1low status was linked to asymptomatic status and notably elevated TCF7 levels." (PMID 40264357, 2025). "At the same time, the transcription of genes related to naïve or memory T cells, such as Sell, Il7r, Tcf7, and Lef1, decreased after infection." (PMID 41459157, 2025). "ScRNA-seq of P14 T cells that were re-isolated at day 3.25 after infection revealed two different Tcf7-expressing precursor clusters." (PMID 39778709, 2025). "At day 7 after infection, the CpG sites in Tcf7 promoter region was 27.1% methylated in antigen specific TH1 cells, which was nearly three times higher than that of 9.1% in antigen specific TFH cells." (PMID 36045674, 2022). "Introducing TCF7 to the lung would probably be a therapeutic way to protect patients from secondary infections through enhancing eomes." (PMID 26289446, 2015). "While it has been shown that the initial dose of MCMV infection dictates the degree of T cell inflation, the numbers of inflationary T cells and the fraction of Tcf7-expressing cells has been demonstrated to remain stable after approximately three weeks post infection." (PMID 35185882, 2022). "There is a need of the direct evidence to show the involvement of TCF7 in the development of pulmonary infection, even though TCF7 may have the close relationship with key lymphocytes in immune responses against infection." (PMID 26289446, 2015). "TCF-7 and IL-7R were downregulated whatever the cause of CRD and this could play a role in the higher susceptibility to infection of these patients." (PMID 25329529, 2014). "Four weeks after infection, the mRNA expression of IFN-γ, TNF-α, and TCF-7 in the lungs of mice was measured." (PMID 33628846, 2021). "We further conducted intracellular cytokine staining (ICS) of lymphocytes in the spleen of WT and Tcf7−/− mice upon stimulation with a peptide (amino acids 33–41, GP33) of the LCMV glycoprotein in vitro at day 8 after Cl13 infection." (PMID 30814995, 2019). "Without CD4 T cells, a significant decrease in the frequency and total number of GP33-tetramer positive Tcf7−/− CD8 T cells in the spleen and liver tissues was observed compared to that in WT counterparts at day 8 post Cl13 infection." (PMID 30814995, 2019). "Consistently, the ICS data presented substantial attenuation of Granzyme B, CD107, and IFNγ production in Tcf7−/− CD8 T cells compared to WT CD8 T cells at both day 8 and day 25 after Cl13 infection." (PMID 30814995, 2019). "To test this hypothesis, we electroporated ribonucleoproteins (RNPs) containing Cas9 and sgRNAs targeting the Tcf7+17kb element in WT or Tcf7Δ+22kb P14 cells, followed by adoptive transfer and LCMV-c13 infection." (PMID 41043414, 2025). "In addition to the Tcf7 locus, we also measured the methylation status of CpG islands at other TFH lineage related gene loci from both control and Ezh2-/- TFH cells at day 8 after infection." (PMID 36045674, 2022).
infection (continued). "Therefore, we sorted antigen-experienced exhausted CD8 T cells (CD44hiPD1hi) at 15 days after infection to extract total RNA of the different subsets of CD8 T cells and conduct array of quantitative real-time PCR (qRT-PCR) to profile the transcriptional signatures of exhausted Tcf7−/− CD8 T cells." (PMID 30814995, 2019).
TCF7 also shares sentences with these, for which no sentence is quoted: Insulin resistance (3 papers); hematologic malignancies (2); lymphoma (2); rectal cancer (2); tuberculosis (2); acute coronary syndrome (1); adenocarcinoma (1); autoimmune disease (1); bladder cancer (1); cardiomyopathy (1); cardiovascular diseases (1); chronic lymphocytic leukemia (1); colitis (1); colorectal tumor (1); craniosynostosis (1); diffuse large B-cell lymphoma (1); endometrial carcinoma (1); esophageal carcinoma (1); gastric cancer (1); HIV-1 infection (1); hypertriglyceridemia (1); immunodeficiency (1); lung adenocarcinoma (1); lupus (1); lymphopenia (1); malignant peripheral nerve sheath tumor (1); mantle cell lymphoma (1); metastatic cancer (1); metastatic prostate carcinoma (1); murine typhus (1).
A further 11 diseases each share a sentence with TCF7 in 1 paper.